INS (insulin)
Diseases named in the same sentence as INS in open-access papers (continued):
Sharing a sentence is not in itself a finding about the gene and the disease.
Hyperglycemia (continued). "Similar to patients, diabetic flies display signs of hyperglycemia, hypertrehalosemia, peripheral resistance to exogenous insulin, and accumulation of triglyceride." (PMID 37123266, 2023). "DM-induced hyperglycemia is characterized by low insulin release, declined glucose use, and high glucose production." (PMID 37848702, 2023). "Our data clearly showed that insulin signaling regulates the heart rate independently of the autonomic nervous system or hyperglycemia." (PMID 37121973, 2023). "In the early stages, hyperglycemia affects different neuronal pathways, including the cholinergic system in the celiac ganglia (impairs glucagon response to insulin)." (PMID 37443762, 2023). "Hyperactivation of Lrp5-dependent signalling had a protective effect in hyperglycaemia and improved peripheral glucose metabolism in an insulin independent manner." (PMID 36674502, 2023). "Lowering [Ca2+]i levels in muscle cells with persistently high [Ca2+]i transforms them from insulin-resistant to non-insulin-resistant, leading to subsequent improvements in hyperglycemia." (PMID 37892970, 2023). "The other source is via an exogenous pathway, in which several factors, namely, intestinal glucose absorption, impaired insulin secretion, incretin dysfunction, and peripheral IR, play essential roles in the generation of postprandial hyperglycemia." (PMID 37653931, 2023). "A total of 382 treatment-naïve patients with recently diagnosed T2D were randomized to receive insulin or oral hypoglycemic agents for rapid initial correction of hyperglycemia." (PMID 37468901, 2023). "Rapid progression of hyperglycemia or an early need for insulin should also prompt to consider this diagnosis." (PMID 37509329, 2023). "In T1D, the immune response to self-antigens leads to the apoptosis of pancreatic β-cells, resulting in lower insulin production and hyperglycemia." (PMID 38140353, 2023). "The dysfunction of pancreatic cells results from hyperglycaemia, and when it is reversed by insulin administration, the functions of β-cells improve and they are regenerated." (PMID 36829539, 2023). "Suppressed insulin secretion contributes to hyperglycemia by increasing the production of glucose in the liver." (PMID 37623224, 2023). "Impaired insulin signaling in the brain contributes to synaptic dysfunction and cognitive deficits, thus linking hyperglycemia to the development/progression of sAD." (PMID 37443762, 2023). "Exenatide reduces fasting and postprandial hyperglycemia by increasing insulin secretion in a glucose-dependent manner, while also suppressing excess glucagon production." (PMID 37685355, 2023). "Chromium(III) (Cr(III)) plays a role in regulating carbohydrate and lipid metabolism, and mediating ghrelin reduction, thereby enhancing insulin sensitivity, ameliorating hyperglycemia, suppressing free radical formation, and reducing SBP." (PMID 37892534, 2023). "The use of needle-free syringes to inject short-acting and rapid-acting insulin therapy can significantly shorten the time of onset of insulin, reverse the glycotoxic effect of hyperglycemia on β cells and significantly enhance the hypoglycemic effect." (PMID 36864833, 2023). "Transplantation of mouse islets with mouse adipose tissue-derived MSCs promoted islet graft survival and insulin function of the graft in streptozotocin-induced diabetic mice and reduced the islet mass required for reversal of hyperglycemia." (PMID 37761001, 2023). "When beta-cell function is impaired, such as in the case of T2DM, insulin secretion is decreased or impaired, which can lead to hyperglycemia (high blood glucose levels)." (PMID 37240157, 2023). "Adiponectin exerts insulin-sensitizing effects and possesses anti-inflammatory activity, and experimental evidence revealed that it ameliorated hyperglycemia in HFD-fed rodents." (PMID 37397470, 2023).
Hyperglycemia (continued). "PHE induces hyperglycemia particularly at toxic concentrations, secondary to the inhibition of insulin release and a subsequent post-binding defect in insulin action." (PMID 37334286, 2023). "All patients who continue to need insulin infusion to maintain their glycemic goals in the ICU need to be transitioned to a scheduled subcutaneous regimen to prevent rebound hyperglycemia when ready to be transferred to a regular nursing floor." (PMID 37120562, 2023). "Persistent hyperglycemia in addition to immobilization leads to a multiplying effect of increased insulin resistance and decreased muscular synthesis, thus enhancing the catabolic effect." (PMID 37547903, 2023). "Rosiglitazone (RSG) is a peroxisome proliferator-activated receptor-gamma agonist that reduces hyperglycemia and hyperinsulinemia and improves insulin signaling." (PMID 37508471, 2023). "Because hyperglycemia also promotes the systemic influx of microbial products from the gut, we examined postprandial excursions of plasma glucose and insulin in response to the test meal challenge and their relationship to serum endotoxin." (PMID 37513677, 2023). "In most cases the insulin was given subcutaneously immediately prior to leaving for the hospital or en route to the hospital upon patient or caregiver recognition of hyperglycemia." (PMID 38165186, 2023). "Hyperglycemia can induce apoptosis and cell death in insulin secreting cells, contributing to IGT and T2D development." (PMID 37758822, 2023). "T2D, a multifactorial condition characterized by reduced insulin production and low insulin sensitivity, is renowned for chronic hyperglycemia." (PMID 38146555, 2023). "In AIS, insulin released post-prandially binds to the insulin antibody resulting in hyperglycaemia, and then as insulin is released from the insulin antibody, hypoglycaemia ensues." (PMID 37892096, 2023). "Deficient autophagy in mice resulting from the knockout of the autophagy-related gene Atg7 leads to impaired glucose tolerance, reduced insulin levels, decreased pancreatic β-cell count, and hyperglycemia." (PMID 37894898, 2023). "There is evidence that prolonged sitting increases insulin concentration and glucose and the ensuing hyperglycaemia alters cerebral glucose utilization kinetics." (PMID 37731204, 2023). "The net result is a viscous cycle of hyperglycaemia leading to continuous deterioration of metabolic function and necessitating insulin therapy in many cases." (PMID 37904255, 2023). "Persons with diabetes who use the Control-IQ system wear the system continuously and direct the pump to deliver insulin boluses for meals and hyperglycemia as needed." (PMID 37614410, 2023). "By the end of 2 weeks of treatment, protein restriction normalized IRFKO mice hyperglycemia, reduced plasma insulin, improved glucose tolerance, and enhanced insulin sensitivity of IRFKO mice to WT levels." (PMID 37479751, 2023). "Chronic hyperglycemia is due to an inability of the body to consistently break down the glucose required to keep up with energy requirements because of peripheral insulin resistance." (PMID 37240215, 2023). "The patient hyperglycemia and ketoacidosis were treated using extracellular fluid and insulin therapy." (PMID 38134115, 2023). "Of patients with NODAT (n = 7), three patients (14.3%) needed insulin therapy and were categorized as having permanent hyperglycemia while four patients (19.1%) had transient hyperglycemia." (PMID 35816203, 2023). "Then, global Rer-erbα/β dual KO mice exhibit hyperglycemia by disturbing the insulin signaling pathway." (PMID 38089624, 2023). "Published data emphasize the prospective beneficial effects of bioactive compounds on lowering hyperglycemia, magnifying insulin secretion, amplifying β-cell function, reducing Aβ accumulation, and strengthening cognitive function." (PMID 36902074, 2023).
Hyperglycemia (continued). "The cure for hyperglycemia requires lowering the hepatic glucose synthesis, improving the insulin action, increasing the release of insulin from pancreatic cells, or inhibiting sugar-digesting enzymes." (PMID 36770873, 2023). "IP6 promotes insulin sensitivity by increasing serum adiponectin levels, leading to reduced diabetic complications, including hyperglycemia and hyperlipidemia." (PMID 37371552, 2023). "This leads to hyperinsulinemia (excessive insulin secretion) and can exacerbate or precipitate hyperglycemia." (PMID 37899888, 2023). "The antioxidant defense mechanism of flavonoids involves the mitigation of reactive oxidative species‐induced endothelial cell damage and endoplasmic reticulum stress responsible for impaired insulin and hyperglycemia." (PMID 36911838, 2023). "In late dumping syndrome, a typical post-gastrectomy syndrome, excessive insulin secretion is known to occur in response to postprandial hyperglycemia." (PMID 37084095, 2023). "DPN-related mechanisms have also been reported to prevent hyperglycemia by promoting glucose uptake by skeletal muscle cells and inhibiting insulin resistance." (PMID 37242603, 2023). "Scheduled insulin therapy should be administered to in patients on glucocorticoid therapy or direct enteral nutrition should they develop hyperglycemia." (PMID 37363479, 2023). "Hyperglycemia is an excess of glucose concentration in the blood which occurs when the pancreas produces too little insulin or when the body cannot use the insulin properly." (PMID 37345014, 2023). "In this study, prior to NAC treatment, hyperglycemia episodes in mice led to decreased insulin content and insulin gene expression." (PMID 37891946, 2023). "Unexpectedly, women with isolated postload hyperglycemia had comparable insulin secretion and sensitivity to euglycemic women, potentially indicative of a novel mechanistic pathway." (PMID 36950879, 2023). "In response to insulin resistance, the insulin secretion capacity of pancreatic β cells is enhanced (known as hyperinsulinemia) to relieve the effect of hyperglycemia during the early stage of T2D." (PMID 37189396, 2023). "As a result, reduced insulin sensitivity and insulin levels lead to hyperglycemia that pushes β-cell metabolic rate to its limits." (PMID 38026205, 2023). "Reduced insulin-stimulated glucose uptake further contributes to hyperglycemia, overburdening the β-cells, which must produce additional insulin in response." (PMID 37512921, 2023). "In T1DM, given that insulin cannot be secreted in response to this hyperglycemic response, the hyperglycemia value often continues to increase after exercise, sometimes becoming dangerous (>400 mg/dL)." (PMID 37998439, 2023). "The beta-cells adapt to these metabolic challenges by producing and secreting more insulin to prevent hyperglycemia." (PMID 36901964, 2023). "Consistent with previous reports, HFD led to hyperglycemia, hyperinsulinemia, and impairments in both glucose tolerance and insulin sensitivity compared to the Chow group." (PMID 36882217, 2023). "Metformin reduces hyperinsulinemia and hyperglycemia by enhancing hepatic and peripheral insulin sensitivity." (PMID 36562831, 2023). "Hyperglycemia and its related complications are the main objectives for conventional management, including diet, insulin, and/or anti-diabetic drugs." (PMID 36839169, 2023). "Women with the most severe GDM with concomitant fasting and postload hyperglycemia demonstrated the most marked changes in insulin secretion, sensitivity, and the plasma lipidome." (PMID 36950879, 2023). "Cardiac muscle cells are insulin-sensitive tissues and glycolysis-dependent tissues, making them vulnerable to hyperglycemia." (PMID 37810881, 2023). "Initially, episodes of alternating hypoglycaemia and hyperglycaemia predominate, and eventually, a progressive decline in insulin levels leads to insulin-resistant diabetes." (PMID 36331627, 2023).
Hyperglycemia (continued). "Both monotherapies increased insulin levels and mitigated hyperglycaemia, dyslipidaemia, renal and urine biochemical profiles alongside renal lipid regulatory molecules, inflammation, and oxidative stress." (PMID 38139208, 2023). "These discrepancies affect the ability of rodents to mimic the pathological features of burn hypermetabolism in humans, including insulin resistance, hyperglycemia, and muscle wasting." (PMID 36779088, 2023). "Loss of beta cells results in an inability to produce and secrete adequate levels of insulin, especially in response to changes in peripheral glucose levels, which can lead to hyperglycemia and several long‐term complications." (PMID 37476069, 2023). "The results of a recent study conducted by the same group provided evidence that the extracts of B. chinensis leaves significantly decreased hyperglycemia, ameliorated insulin sensitivity, and prevented hepatic gluconeogenesis in KK-Ay mice." (PMID 37111281, 2023). "Although the early phase of damage is associated with increased insulin release as a compensatory mechanism, prolonged hyperglycemia and ROS release deteriorate the pancreatic islets and promote more β-cell damage and ultimately reduced insulin release." (PMID 37397470, 2023). "The evening after the exercise test, three people (17%) in CON, one (6%) in D40 and one (6%) in D20-P injected additional short-acting insulin because of profound hyperglycaemia." (PMID 36879098, 2023). "In general, such control is possible by the administration of exogenous insulin or oral drugs, which reduces hyperglycemia events." (PMID 37794521, 2023). "The activation of PPARγ is a key mechanism for ameliorating hyperglycemia, and IR and PPARγ agonists, such as PIO, increase insulin sensitivity and ameliorate hyperglycemia, dyslipidemia, OS, and inflammation." (PMID 37397470, 2023). "Lack of insulin secretion in T1D and a combination of IR with an inadequate compensatory response to insulin secretion in T2D lead to hyperglycaemia and, consequently, to macro and microvascular diseases." (PMID 38136211, 2023). "Nevertheless, these are parameters that need further studies to decipher how they can alter INS and other pre-mRNAs in multiple conditions affecting endocrine cells including aging, hyperglycemia, and inflammation among others." (PMID 37127706, 2023). "Continuous monitoring of glucose allows diabetic patients to better maintain blood glucose level by altering insulin dosage or diet according to prevailing glucose values and thus to prevent potential hyperglycemia and hypoglycemia." (PMID 36646501, 2023). "Undoubtedly, physical activity reduces the probability of T2DM by increasing insulin sensitivity and glucose tolerance, leading to the prevention of hyperglycemia." (PMID 36975496, 2023). "Postprandial hyperglycemia is driven by many factors such as timing, quantity, meal composition, carbohydrate content, insulin and glucagon secretion, among others." (PMID 36900596, 2023). "Hyperglycemia occurs only when islet inflammation impairs the function of β cells, preventing them from producing enough insulin to compensate for insulin resistance." (PMID 37706196, 2023). "In the circumstances of IR, target tissues including skeletal muscle, liver, and adipose tissue cannot provide an expected response under normal insulin level; therefore, pancreatic beta-cells secrete more insulin to overcome hyperglycaemia." (PMID 37471338, 2023). "If DKA occurs in the context of pre-existing T1DM, the patient’s basal analogue insulin should be continued alongside the insulin infusion so that rebound hyperglycaemia is prevented after intravenous insulin is stopped." (PMID 37568965, 2023). "GLP-1 RAs exert a dual action on the endocrine pancreas cells, with a stimulation of insulin secretion by b-cells, mainly in the postprandial state, and an inhibition of glucagon secretion by a-cells, contributing to reducing hyperglycemia." (PMID 37626624, 2023).
Hyperglycemia (continued). "Of the NCDs, DM is a group of metabolic diseases characterized by hyperglycemia that results from defects in insulin secretion, insulin sensitivity, or both." (PMID 37947527, 2023). "Impaired insulin secretion due to the destruction of beta cells of the pancreas, hyperglycemia due to stress, and steroids in patients with COVID-19 infection can all contribute to the development of new-onset diabetes mellitus." (PMID 36769807, 2023). "Insulin initiation is also recommended in treatment naïve individuals if they have symptomatic hyperglycemia and the glycated hemoglobulin levels are >9%." (PMID 36650625, 2023). "Compensatory hyperinsulinemia develops as an early response to burn-induced hyperglycemia, subsequently followed by lowered insulin levels." (PMID 36779088, 2023). "Recently, a robust CRISPR/Cas9 target gene activation (TGA) technology promoted in vivo trans-differentiation of liver cells into insulin-producing cells and ameliorated hyperglycemia by increasing serum insulin levels in STZ-treated diabetic mice." (PMID 37008919, 2023). "Treatment involves fluid resuscitation, insulin administration to correct hyperglycemia, correction of acidosis, electrolyte imbalances, and treatment of underlying causes or precipitants." (PMID 37363479, 2023). "During gestational diabetes, β-cells fail to secrete insulin for the demands of pregnancy, and, when combined with reduced insulin sensitivity, this results in hyperglycemia." (PMID 36986107, 2023). "Through the regulation of PPAR-mediated glucose and lipid metabolism, cinnamon extract has been proposed to improve hyperglycemia and hyperlipidemia, increase insulin sensitivity, and lower blood and hepatic lipids." (PMID 37408757, 2023). "Women with early‐onset GDM had 6.7% (95% CI 0.7%–12.7%) lower SHBG levels and women who needed insulin for fasting hyperglycaemia 8.7% (95% CI 1.8%–14.8%) lower SHBG levels than other women with GDM." (PMID 36484476, 2023). "STZ inhibits the secretion of insulin in the Langerhans islet beta cell, which leads to hyperglycemia complications such as endothelial cell dysfunction." (PMID 36771275, 2023). "The proposed mechanism for this unexpected finding is that the majority of insulin is no longer stored in its hexameric form and that, in response to hyperglycaemia, can be released more rapidly as insulin is already in a soluble form." (PMID 37396167, 2023). "Patients with this condition require lifelong insulin administration to prevent hyperglycemia and ketoacidosis." (PMID 37370930, 2023). "Opium consumption was associated with hyperinsulinemia due to changes in hepatic extraction of insulin, hyperglycemia similar to what is seen in type 2 DM, and also high levels of glycated hemoglobin (HbA1c) and poor glycemic control." (PMID 36874455, 2023). "Accelerated lipolysis in visceral fat leads to free fatty acid mobilisation, resulting in hyperglycaemia and hepatic insulin resistance." (PMID 37592236, 2023). "Insulin enhances constitutive eNOS expression in endothelial cells, while hyperglycemia and AGEs reduce eNOS activity." (PMID 36979641, 2023). "GSIS is a variant of the glucose tolerance test during which the medium is sampled at key time points to measure insulin levels in the basal state and after induction of hyperglycemia by glucose." (PMID 37195917, 2023). "Insulin is the most effective agent for hyperglycemia control due to its ability to be adjusted infinitely." (PMID 38063570, 2023). "The administration of this conjugated bile acid to obese and diabetic mice normalizes hyperglycemia, restores systemic insulin sensitivity, improves fatty liver, and enhances insulin actions in liver, muscle, and adipose tissues." (PMID 36458804, 2023). "DM is a metabolic disorder characterized by hyperglycemia and insufficient insulin secretion or function." (PMID 38113243, 2023).